PILRB (paired immunoglobin like type 2 receptor beta)
Description:
Paired receptors consist of highly related activating and inhibitory receptors and are widely involved in the regulation of the immune system. PILRB is thought to act as a cellular signaling activating receptor that associates with ITAM-bearing adapter molecules on the cell surface.
Synonyms: FDFACT1; FDFACT2
Tractability: Antibody: its Gene Ontology location is reachable by antibodies, with high confidence; UniProt predicts a signal peptide or a membrane-spanning region.
Gene: Protein-coding gene on chromosome 7 (100,352,176 to 100,367,831, forward strand). Ensembl gene ENSG00000121716.
Subcellular location: Membrane
Subcellular location (Human Protein Atlas): Mitochondria
Pathways (Reactome):
Immune System: Immunoregulatory interactions between a Lymphoid and a non-Lymphoid cell
Gene Ontology:
Molecular function: protein binding; MHC class I protein binding
Biological process: activation of transmembrane receptor protein tyrosine kinase activity; cell surface receptor protein tyrosine kinase signaling pathway
Cellular component: plasma membrane; membrane
Genetic constraint (gnomAD): Loss-of-function variants: 21 observed, 23.15 expected, observed/expected ratio (o/e) 0.91, 90% interval 0.64 to 1.31. The upper end of that interval is the gene's LOEUF score, 1.31, which puts it in group 5 of 6, group 1 being the genes least tolerant of losing a copy. Missense variants: 242 observed, 275.42 expected, observed/expected ratio (o/e) 0.88, 90% interval 0.79 to 0.98. Synonymous variants: 128 observed, 114.61 expected, observed/expected ratio (o/e) 1.12, 90% interval 0.97 to 1.29.
Homologues: Paralogues in human: PILRA (83% identical).
Diseases named in the same sentence as PILRB in open-access papers:
PILRB is named in the same sentence as 17 diseases in open-access papers, as found by Europe PMC text mining. Sharing a sentence is not in itself a finding about the gene and the disease. The quoted sentences say what the papers report.
age-related macular degeneration (1 paper, 2018). Age-related loss of vision in the central portion of the retina (macula), secondary to retinal degeneration. "Of interest, the G allele of rs6955367 (increased expression of PILRB) is linked to rs7803454 (r2 = 0.83), a variant associated with increased risk of age-related macular degeneration and suggests the presence of independent effects in the PILRA/PILRB region." (PMID 30388101, 2018).
Alzheimer disease (1 paper, 2018). A progressive, neurodegenerative disease characterized by loss of function and death of nerve cells in several areas of the brain leading to loss of cognitive function such as memory and language. "The relevant ligands for PILRA/PILRB in vivo and the mechanism by which reducing PILRA-ligand interaction confers protection from Alzheimer’s disease remain to be elucidated." (PMID 30388101, 2018).
gastric cancer (1 paper, 2024). A primary or metastatic malignant neoplasm involving the stomach. "Firstly, the levels of PILRB are upregulated in human gastric cancer (GC) specimens and associated with poor prognosis in patients with GC." (PMID 39227585, 2024).
gastric tumors (1 paper, 2024). "In our report, we verified that PILRB was upregulated in gastric tumors compared to adjacent normal tissues, and its upregulation predicts poor survival outcomes." (PMID 39227585, 2024).
metabolic syndrome (1 paper, 2023). A cluster of metabolic risk factors for CARDIOVASCULAR DISEASES and TYPE 2 DIABETES MELLITUS. "Seven metabolic syndrome-related genes (CSF3R, TMEM132A, STAB1, VIM, DUOXA1, PILRB, and SLC2A4) were used to construct risk equations." (PMID 37033267, 2023).
stomach adenocarcinoma (1 paper, 2024). "Exploring the function of PILRB in GC progression, we observed that in TCGA database, PILRB mRNA levels were significantly upregulated in stomach adenocarcinoma (STAD) samples compared with that in normal tissues." (PMID 39227585, 2024).
infection (4 papers, 2012 to 2025). The state of being infected such as from the introduction of a foreign agent such as serum, vaccine, antigenic substance or organism. "PILRB is expressed in inflammatory macrophages, natural killer cells, dendritic cells, and microglial cells, all of which contribute to the production of inflammatory factors during infection." (PMID 40050982, 2025). "The MAG ECD was fused with transmembrane/intracellular domains of activating paired immunoglobulin-like receptor b (PILRb) in this system, followed by infection into murine T-cell hybridoma cells with a nuclear factor of activated T cells (NFAT)/GFP reporter gene." (PMID 36855057, 2023). "Pattern "Virulent", in contrast, includes 1,165 genes whose expression levels were less strongly changed after infection with heat-inactivated MTB H37Rv or the attenuated vaccine strain BCG compared to the other bacteria (e.g. IL1R1, IRF1, PILRB)." (PMID 26586179, 2015).
tumor (4 papers, 2022 to 2025). "The results showed that PILRB-depleted AGS/MKN-28 cells significantly suppressed the increase in tumor volume over the entire assay period and decreased the final tumor weight in the subcutaneous xenograft models." (PMID 39227585, 2024). "In the future, a larger clinical sample cohort size would be valuable to verify the expression of the PILRB protein of GC patients in the tumor tissues of GC patients with and without metastasis Therefore, we investigated the oncogenic role of PILRB in GC cells both in vitro and in vivo." (PMID 39227585, 2024).
cancer (2 papers, 2022 to 2024). A tumor composed of atypical neoplastic, often pleomorphic cells that invade other tissues. "To explore the molecular mechanisms underlying the oncogenic role of PILRB, we performed RNA-sequencing in the deficiency of PILRB and control AGS/MKN28 cancer cells." (PMID 39227585, 2024). "Moreover, PILRB might be a wider clinical biomarker for lowering cholesterol level-dependent gastric and other cancer types." (PMID 39227585, 2024). "Furthermore, the IHC assay showed that PILRB protein levels were higher in cancer samples." (PMID 39227585, 2024). "Paired immunoglobin-like type 2 receptor beta (PILRB) mainly plays a crucial role in regulating innate immunity, but whether PILRB is involved in cancer is poorly understood." (PMID 39227585, 2024). "Our work also provides evidence that PILRB may prove to be of wider clinical relevance as a biomarker for PI3K/AKT pathway-dependent GC and other cancers." (PMID 39227585, 2024).
PILRB also shares sentences with these, for which no sentence is quoted: bladder cancer (2 papers); clear cell renal cell carcinoma (1); colorectal cancer (1); encephalitis (1); neurodegenerative disease (1); ovarian carcinoma (1); renal papillary cell carcinoma (1); schizophrenia (1).